HIF1A (hypoxia inducible factor 1 subunit alpha)
Diseases named in the same sentence as HIF1A in open-access papers (continued):
Sharing a sentence is not in itself a finding about the gene and the disease.
pancreatic cancer (continued). "Dominant-negative HIF-1α was shown to suppress pancreatic cancer cell growth under hypoxic and glucose-deprived conditions." (PMID 22211243, 2012). "Here, we report that hypoxia or overexpression of hypoxia-inducible factor-1α (HIF-1α) promotes EMT in pancreatic cancer cells." (PMID 21887310, 2011). "As shown by Western blotting, HIF-1α protein levels in pancreatic cancer cells were up-regulated during hypoxia." (PMID 21887310, 2011). "We provide evidence that BITC dose-dependently inhibits the migration, invasion, and neovascularization of human pancreatic cancer and endothelial cells by targeting HIF1α, VEGF, MMP-2, and Rho-GTPases through the STAT-3 dependent pathway." (PMID 22016776, 2011). "Introducing a pcDNA3.0/HIF-1α into pancreatic cancer cells under normoxic conditions heightened NF-κB activity, phenocopying EMT effects produced by hypoxia." (PMID 21887310, 2011). "Taken together, these results suggest that hypoxia or overexpression of HIF-1α induce the EMT that is largely dependent on NF-κB in pancreatic cancer cells." (PMID 21887310, 2011). "Interrupting this loop in pancreatic cancer cells at one or more of the many biochemical steps that link HIF-1α to NF-κB is apt to have a significant effect on pancreatic cancer growth." (PMID 21887310, 2011). "Our data presented herein indicated that NF-κB activation is increased under hypoxic conditions as well as transiently transfected with a pcDNA3.0/HIF-1α in pancreatic cancer cells under normoxic conditions." (PMID 21887310, 2011). "One of the main observations that revealed the important intra-tumoral hypoxia in pancreatic cancer is the elevation of Hypoxia-inducible factor-1α (HIF-1α), the major transcription factor activated under hypoxic conditions." (PMID 24281221, 2010). "Using HIF-1α expression as a marker for tumour hypoxia, we demonstrate that in both differentiated and undifferentiated pancreatic tumours HIF-1α protein is stabilised." (PMID 16832411, 2006). "Recently we have reported that most pancreatic cancer cells, which are known to show high invasiveness and high metastatic potential in vivo, over-expressed HIF-1α proteins constitutively." (PMID 12085186, 2002). "The function of ALDOA in pancreatic cancer could be attributed to its regulatory role of HIF1α and c-Myc." (PMID 39755705, 2025). "For example, in pancreatic cancer, constitutively expressed HIF-1α activates anaerobic metabolic pathways, enabling pancreatic cancer cells to survive and proliferate in hypoxic and nutrient-deprived environments, thereby increasing their resistance to apoptosis." (PMID 41311849, 2025). "Meanwhile, the study also indicated that circ_0000977 may be involved in HIF-1α mediated immune escape of pancreatic cancer cells from immune surveillance and NK cell-mediated lysis." (PMID 39928285, 2025). "For example, the crosstalk between MUC1 and HIF-1α signaling increases glycolytic flux, leading to increased pyrimidine synthesis in tumor cells, which competes with GEM, reducing its toxicity and causing chemoresistance in pancreatic cancer." (PMID 39990228, 2025). "HIF-1α plays a central role in the carcinogenesis and progression of pancreatic cancer." (PMID 41150799, 2025). "HIF-1α plays an important role in the occurrence and development of pancreatic cancer." (PMID 40563539, 2025). "Therefore, the upregulation of SIRT1 enhances the stability of the HIF-1α protein through deacetylation, promoting Gemcitabine resistance in normoxic pancreatic cancer cells." (PMID 39928285, 2025). "Targeting HIF-1α and its signaling pathways could hold promise as a therapeutic approach for pancreatic cancer." (PMID 41150799, 2025). "The activity of HIF-1α is modified by microRNA-27a to increase autophagy in pancreatic cancer." (PMID 40004215, 2025).
pancreatic cancer (continued). "LncRNAs, in addition to having a role in PDAC development, also play an important role in GEM resistance, e.g., HIF1A-AS1 significantly up-regulates lncRNAs in GEM-R pancreatic cancer cells and triggers glycolysis-associated GEM resistance by regulating the translation of the justice gene HIF-1α." (PMID 40630951, 2025). "In combination chemotherapy, HIF-1α inhibition may alleviate hypoxic microenvironments in pancreatic cancer, improving the delivery efficiency of chemotherapeutic agents like gemcitabine." (PMID 40406267, 2025). "Previous studies have demonstrated that Arhgap25 regulates the proliferation of human pancreatic cancer cells via HIF-1α, leading us to hypothesize that RhoA modulates glycolytic processes through Arhgap25/HIF-1α pathway." (PMID 40846818, 2025). "The NKG2D receptor of NK cells in pancreatic cancer patients with high expression of HIF-1α was internalized, then lost the ability to bind to NKG2D ligands on the surface of tumor cells, and NK cells could not exhibit cytotoxicity to pancreatic cancer cells." (PMID 40563539, 2025). "Researchers have explored how HIF-1α regulates tumorigenesis and progression in pancreatic cancer." (PMID 41150799, 2025). "Moreover, inhibiting the upstream signals of HIF-1α in pancreatic cancer can also effectively reduce the expression of MMPs." (PMID 40563539, 2025). "Also, a study conducted using pancreatic cancer cells indicates that HIF-1α regulates the EMT and invasion of cancer cells through hedgehog signaling." (PMID 38361941, 2024). "Based on these observations, it could be proposed that lowered PHD2 oxidation might impair its catalytic activity, thus leading to the elevation of HIF-1a protein abundance and the enhancement of target gene expression to promote pancreatic cancer development." (PMID 38493183, 2024). "For instance, HIF‐1α induced NR2F1‐AS1 upregulation in pancreatic cancer (PC) and highly expressed NR2F1‐AS1 promoted PC cell proliferation, migration, and invasion by modulating the expression of its sense gene NR2F1, which activates the AKT/mTOR pathway in PC." (PMID 39224045, 2024). "Thus, targeting HIF-1α is a promising therapeutic strategy for overcoming chemo-resistance and reducing metastatic potential in pancreatic cancer and other tumors." (PMID 39458615, 2024). "Thus, the interaction of RKIP with HIF-1α can protect against pancreatic cancer metastasis by inhibiting its hypoxia function." (PMID 38786085, 2024). "AKT is known to induce glycolysis through HIF1α induction in pancreatic cancer." (PMID 38425123, 2024). "In addition, HIF-1α is overexpressed in many other types of cancer, including clear cell renal cell carcinoma, head and neck cancer, and pancreatic cancer." (PMID 39194515, 2024). "The development and metastasis of pancreatic cancer could also be promoted by hypoxia-induced HIF-1a overexpression, mediated by the expressional activation of various functional genes." (PMID 38493183, 2024). "Given the role of the PVT1/HIF-1α regulatory loop in the progression of pancreatic cancer, this path may be one of the promising therapeutic goals in managing pancreatic cancer." (PMID 38559560, 2024). "Pancreatic cancer is known to be a hypoxic tumor, where HIF1a is overexpressed." (PMID 38425123, 2024). "This approach effectively suppressed the expression of HIF-1α and genes responsible for glucose uptake and cancer cell metabolism, thus inhibiting the growth of orthotopic desmoplastic pancreatic cancer in NSG mice and reversing the chemotherapy resistance induced by hypoxia." (PMID 38338746, 2024). "Previous research has shown that the cytoplasmic tail of MUC1 physically interacts with and blocks the proteasomal degradation of HIF-1α in pancreatic cancer cell lines and animal models, and higher expression of MUC1 was observed in gemcitabine-resistant cells." (PMID 38540735, 2024).
pancreatic cancer (continued). "Furthermore, the inhibition of Beclin1 expression was demonstrated to result in a reduction in the binding between Beclin1 and HIF-1α in hypoxic pancreatic cancer cells." (PMID 39062777, 2024). "Congruently, in this study, we aimed to demonstrate whether HDAC4 could enhance the stability of HIF1a in hypoxic pancreatic cancer cells." (PMID 37149664, 2023). "Molecular docking experiments suggested that resveratrol may be a direct inhibitor of HIF1α; it down-regulates its protein level in pancreatic cancer cells." (PMID 38001865, 2023). "Therefore, ALKBH5, HDAC4 and HIF1α form a positive feedback loop in PC cells under hypoxic conditions and contribute to pancreatic cancer progression." (PMID 37149664, 2023). "Furthermore, upregulation of LINC00460 in pancreatic cancer is induced by HIF-1α under hypoxic conditions." (PMID 37786443, 2023). "In addition, in pancreatic cancer (PC), the circ-0000977/miR-153/HIF1α axis promoted the immune evasion of PC cells by inhibiting the cytotoxicity of NK cells." (PMID 36672208, 2023). "In our study, we investigated the effect of 8a on the angiogenesis of pancreatic cancer and found that 8a could inhibit the expression of CD31 and HIF-1α, indicating that 8a also has an inhibitory effect on angiogenesis in pancreatic cancer." (PMID 37888452, 2023). "In addition, overexpressing HIF1a promoted the transcription of ALKBH5 in hypoxic pancreatic cancer cells." (PMID 37149664, 2023). "In this positive feedback loop, circZNF91 upregulated SIRT1 expression via competitively binding to miR-23b-3p and SIRT1 stabilizes HIF-1α protein via decreasing the acetylation of HIF-1α in pancreatic carcinoma (PC) cells,thus increasing the protein level of HIF-1α." (PMID 37213665, 2023). "Another study in pancreatic cancer cells showed that circ-0000977, a hypoxia-inducible circRNA, could regulate the killing effect of NK cells through HIF1A and ADAM1039." (PMID 36369467, 2022). "Graviola, which is extracted from Annona Muricata, could inhibit glucose uptake in pancreatic cancer cells by suppressing the expression of HIF-1α, NF-κB, GLUT1/GLUT4, HK2 and LDHA according to a recent study, thereby decrease ATP generation." (PMID 36339566, 2022). "In addition, MUC1 can increase the carbon flux of the non-oxidative pentose phosphate pathway (PPP) and pyrimidine synthesis pathway of pancreatic cancer cells by promoting the expression of HIF-1α, leading to gemcitabine resistance." (PMID 35879749, 2022). "Notably, lncRNA CASC9 promotes glycolytic metabolism and EMT in pancreatic cancer through a positive feedback loop with AKT/HIF1α, and hypoxia conditions will synergistically amplify this biological effect." (PMID 35651786, 2022). "HIF1A up-regulates miR-21 to suppress apoptosis of pancreatic cancer cells." (PMID 36139919, 2022). "In addition, hypoxia-induced circ_0000977 facilitates the immune escape of pancreatic cancer cells by absorbing miR-153 to abrogate the inhibition of HIF-1α and ADAM10." (PMID 35915091, 2022). "In pancreatic cancer, hypoxia upregulates HIF-1α expression in both cancer cells and fibroblasts." (PMID 35884382, 2022). "HIF-1α was also reported to promote glycolysis in pancreatic cancer by regulating NRP136." (PMID 33850110, 2021). "Several studies have confirmed the role of HIF-1α in promoting glycolysis in pancreatic cancer." (PMID 34540683, 2021). "A recent study had found that LSMS1 could promote the survival of pancreatic cancer cells under oxygen-glucose deprivation condition by enhancing HIF1A protein translation and activating AKT/TOR signaling." (PMID 33816550, 2021). "Moreover, the regulation of TLR4 mediated by HIF-1α has been confirmed by knockdown experiments in which HIF-1α depletion is associated with inhibition of hypoxia-induced TLR4 overexpression and to pancreatic cancer regression." (PMID 34884547, 2021).
pancreatic cancer (continued). "The increased expression of VEGF and, therefore, angiogenesis due to HIF-1α could promote the progression of pancreatic tumors." (PMID 34885243, 2021). "Also, miR-548an, a tumour suppressor miRNA, is down-regulated by HIF-1α in pancreatic cancer cells, and it is involved in increasing vimentin level and facilitating the pancreatic tumorigenesis." (PMID 33673376, 2021). "A recent report showed that ST6GAL1 increases HIF-1α accumulation in ovarian and pancreatic cancer cells grown in a hypoxic environment, and induced the expression of HIF-1α transcriptional targets, including the glucose transporters GLUT1 and GLUT3 and the glycolytic enzyme PDHK1." (PMID 33921986, 2021). "In addition, hypoxia and the subsequent stabilization of HIF-1α promotes EMT in pancreatic cancer cells through NF-κB and TGF-β signaling." (PMID 33808542, 2021). "Interestingly, a recent study on pancreatic cancer has reported that MIIP leads to destabilization of HIF-1α by inhibiting the deacetylase activity of HDAC6 and thereby enhancing HIF-1α acetylation." (PMID 34931765, 2021). "Among these, the induction of TLR4 receptor by hypoxia-inducible transcription factor 1 alpha (HIF-1α) may facilitate pancreatic cancer growth as demonstrated in vitro by the exposure of PANC1 cells to hypoxic stress." (PMID 34884547, 2021). "Interestingly, HIF-1α is recently being pursued as a potential target of PDAC treatment as chemoresistant pancreatic cancer cells were shown to exhibit increased glycolysis, which is partly regulated by HIF-1α." (PMID 33546284, 2021). "Plk1 expression correlated with HIF-1α target in 15 out of 26 available data on cancer types (enough data for robust statistical analysis in 26 out of 32 available cancer types) like melanoma, two types of kidney, head and neck, lung, and pancreatic cancers." (PMID 33547392, 2021). "Furthermore, it was demonstrated that FEZF1-AS1 is increased by hypoxia, positively regulates HIF-1α expression via repressing the activity of miR-142-3p under hypoxia, and ultimately promotes cell invasion in pancreatic cancer." (PMID 34298879, 2021). "In addition, HIF-1α also plays an essential role in regulating the cellular metabolism and the increasing anti-apoptotic capacity of pancreatic cancer cells." (PMID 34207699, 2021). "HIF1A is known to regulate cellular adaption to hypoxic conditions and plays important roles in several cancers, including head and neck cancer, ovarian cancer and pancreatic cancer." (PMID 33663502, 2021). "Importantly, based on our mechanistic biomarkers HIF1α and Gal3, we predicted that pancreatic cancers are particularly well amenable to Hsp90 inhibitor treatment, as both of these biomarkers are highly expressed in that cancer type." (PMID 34199986, 2021). "In pancreatic cancer cells, over-expression of miR-142, normally reduced under hypoxic condition, significantly affects cell proliferation and migration by downregulating HIF-1α." (PMID 33673376, 2021). "In pancreatic cancer, circ_0000977 was revealed to regulate the miR-153 downstream targets of hypoxia-inducible factor 1-alpha (HIF1A), a disintegrin, and Metalloproteinase Domain 10 to modulate HIF1A-mediated immune escape of pancreatic cancer cells from NK cells." (PMID 33710802, 2021). "We demonstrate for the first time that incubating KLM-1 pancreatic cancer cells with oxLDL shifts the energy balance towards a more glycolytic phenotype, which is supported by oxLDL-induced stabilization of hypoxia-inducible factor 1-alpha (HIF-1α), a master regulator of glycolysis." (PMID 34475995, 2021). "Analogously to what we have recently published for conglobatin A, elaiophylin may have a high efficacy in KRAS mutant cancers with high HIF1α and Gal3 levels, which is particularly the case in pancreatic cancer." (PMID 34199986, 2021).
pancreatic cancer (continued). "Furthermore, the knockdown of HIF-1a and HIF-2a in pancreatic cancer cells revealed that miR-301a-3p expression level under hypoxia conditions relied on HIF-1a and HIF-2a." (PMID 35059436, 2021). "Other putative STAT3 targets were DPYD, a gene encoding a key 5-FU-metabolizing enzyme, MUC1, which impacts on the response to radiotherapy in pancreatic cancer, and HIF1A, an established target of JAK-STAT signaling and previously reported as potential determinant of tumor radiosensitivity." (PMID 33530306, 2021). "Nevertheless, infection of pancreatic cancer cells with oncotropic H-1 parvovirus could rapidly degrade HIF-1α in a proteasome-dependent manner in hypoxia, and this process was independent of Von Hippel–Lindau and receptor of activated protein C kinase." (PMID 32587480, 2020). "Therefore, we performed the further mechanism study in present study, and the results showed that downregulation of c-Myc enhanced the antitumor activity of bufalin on pancreatic cancer cells by suppressing the HIF-1α/SDF-1/CXCR4 pathway." (PMID 32362830, 2020). "The research indicated upregulation of TCF7L2 inhibited the promoter activity of Egl-9 family hypoxia-inducible factor 2 (EGLN2) and suppressed its expression, which enhanced the stability of HIF-1α, enhancing glycolysis-related genes expression and increasing glycolysis in pancreatic cancer cells." (PMID 32587480, 2020). "Interestingly, tissue microarray analyses of pancreatic tumor clinical specimens showed that Mint3 expression is also correlated with HIF-1α expression." (PMID 32826949, 2020). "Intriguingly, HIF-1α could also mediate stress-induced pancreatic tumor growth and angiogenesis via regulating the expression of VEGF, matrix metalloproteinase 2 (MMP-2) and matrix metalloproteinase 9 (MMP-9)." (PMID 32587480, 2020). "This article reviewed the molecular mechanisms of how HIF-1α regulated tumorigenesis and progression of pancreatic cancer and suggested that targeting HIF-1α and its signaling pathways could be promising therapeutics for pancreatic cancer." (PMID 32587480, 2020). "Moreover, CD133 elevated HIF-1α transcriptional activity in pancreatic cancer cells in hypoxia, initiating its expression and activating its target genes, which in turn induced EMT phenotype and tumor cells migration." (PMID 32587480, 2020). "However, current researches have consistently revealed that HIF-1α is overexpressed in patients with pancreatic cancer and regulated various genes expression, acting as an oncogene in pancreatic cancer." (PMID 32587480, 2020). "This suggests novel therapeutic strategies targeting HIF-1α and its signaling pathways might be promising for pancreatic cancer therapy." (PMID 32587480, 2020). "Similarly, HS-345, an inhibitor targeting tropomyosin-related kinase A, and HS-527, an inhibitor of PI3K, inhibit angiogenesis via targeting HIF-1α/VEGF axis in pancreatic cancer." (PMID 32587480, 2020). "Therefore, the involvement of HIF-1α in the regulation of apoptosis in pancreatic cancer in hypoxia requires further exploration." (PMID 32587480, 2020). "Moreover, β-AR agonists, especially the β2-AR agonist, activate epidermal growth factor receptor (EGFR) and then Akt and ERK1/2 in a PKA-dependent manner, which in turn upregulate HIF-1α in pancreatic cancer cells even under normoxic conditions." (PMID 33419318, 2020). "Inhibiting HSP90 could reverse HIF-1α-mediated resistance to radiotherapy and chemotherapy in pancreatic cancer." (PMID 32587480, 2020). "Hypoxia increased the expression of SHH in a HIF-1α-dependent manner, and its overexpression activated HH signaling and collagen Ι fibronectin formation, inducing desmoplasia and enhancing tumor aggressiveness in pancreatic cancer." (PMID 32587480, 2020).